DCLK1 (doublecortin like kinase 1)
Diseases named in the same sentence as DCLK1 in open-access papers (continued):
Sharing a sentence is not in itself a finding about the gene and the disease.
pancreatic cancer (continued). "DCLK1 has previously been linked to the pro-oncogenic CSC markers c-MET and c-MYC, and gene set enrichment analysis demonstrated that DCLK1-IN-1 affected MET-driven oncogenesis in patient-derived pancreatic cancer organoids." (PMID 34830884, 2021). "The miR-15 family regulates key stemness markers such as BMI-1 and DCLK1 in pancreatic cancer." (PMID 33562727, 2021). "Even though DCLK1 has emerged as a cancer stem cell marker candidate for pancreatic cancer, intestinal cancer, and colorectal cancer, the structural knowledge of the putative inhibitors with various types of scaffolds targeting the DCLK1 kinase domain remains currently limited." (PMID 34445192, 2021). "In particular, LRRK2-IN-1 (XMD11-50), another creation of the Gray lab, developed to target the key Parkinson’s disease target LRRK2, has been used to study potential effects of DCLK1 kinase inhibition in colorectal cancer, pancreatic cancer, head and neck cancer, and cholangiocarcinoma." (PMID 34830884, 2021). "One study suggested that the overexpression of miR-195 inhibits the proliferation, migration, and invasion of pancreatic cancer cells and that its levels inversely correlate with doublecortin-like kinase 1, a tumor-specific stem cell marker in pancreatic cancer." (PMID 34440625, 2021). "As observed in pancreatic tumor xenograft models, siRNA-mediated knockdown of DCLK1 or downregulation by a kinase inhibitor XMD8-92 leads to the decreased expression of angiogenic markers/vascular endothelial growth factor (VEGF) receptors (VEGFR1 and VEGFR2) and EMT-TFs ZEB1, ZEB2, Snail, and Slug." (PMID 34453639, 2021). "In pancreatic tumors, it has recently been shown that immune cell-derived IL-17 regulates the development of TCs via increased expression of DCLK1, POU domain class 2 transcription factor 3 (POU2F3), aldehyde dehydrogenase 1 family member A1 (ALDH1A1), and IL17RC." (PMID 33348546, 2020). "Notably, DCLK1 has been identified as a potential RAS effector and activator in multiple studies, and DCLK1 expression in pancreatic cancer patients is correlated with RAS downstream signaling pathways ERK, PI3K, and MTOR." (PMID 33348546, 2020). "Several studies also indicated that downregulating DCLK1 expression or inhibiting its kinase activity leads to growth arrest of colorectal, pancreatic, and renal cancers as well as decreases metastasis of colorectal and pancreatic cancers." (PMID 31979136, 2020). "Doublecortin-like kinase 1 (DCLK1), a putative marker of intestinal and pancreatic stem cells, regulates the pluripotency and expression of angiogenic factors via miRNA-dependent mechanisms in pancreatic cancer." (PMID 33198082, 2020). "Both KDM3A and DCLK1 mRNA levels are higher in human pancreatic tumor tissues than in non-tumor pancreatic tissues, and their expression is correlated with shorter survival times of patients with pancreatic cancer." (PMID 32354028, 2020). "Doublecortin-like kinase 1 (DCLK1) is often overexpressed in pancreatic cancer and is coexpressed with other PDAC CSC markers, and recent studies indicate that DCLK1+ PDAC cells can initiate pancreatic tumorigenesis in the presence of mutation and inflammation." (PMID 31467540, 2019). "Initial studies have provided preliminary evidence that both pre-invasive and invasive pancreatic cancers depend for their growth on DCLK1-positive cells with CSC properties and that these cells highly express ABL1 and IGF1R, both required for their oncogenic properties." (PMID 29156578, 2017). "Using a model of liver invasive pancreatic cancer, Ito and coworkers showed that DCLK1+ cells were predominantly expressed at the level of cells with CSC properties: these cells were highly metastatic and preferentially localized at the level of invading tumor margins." (PMID 29156578, 2017). "Clinically, DCLK1 was overexpressed in the metastatic tumors in patients with pancreatic cancer." (PMID 26764906, 2016).
pancreatic cancer (continued). "Our studies revealed that DCLK1 is essential for the invasive and metastatic properties of CSCs and may be a promising epigenetic and therapeutic target in human pancreatic cancer." (PMID 26764906, 2016). "The development and progression of pancreatic cancer have also been shown to depend on DCLK1+ TSCs." (PMID 27335684, 2016). "Similarly, DCLK1 was shown to mark a morphologically distinct subpopulation of cells with stem cell properties in pre-invasive pancreatic cancer." (PMID 26673007, 2016). "The function of DCLK1 in human pancreatic cancer cells may thus be to control the action of microtubules." (PMID 26764906, 2016). "DCLK1 may be an essential factor in invasion and metastatic mechanisms and therefore could be a promising therapeutic target for treatment of pancreatic cancer." (PMID 26764906, 2016). "DCLK1 however, was found in the islets, ducts and a few intervening stromal cells in chronic pancreatitis, and even more intense DCLK1 expression was found in ductal epithelial cells and in intervening stromal elements in pancreatic cancer." (PMID 25723399, 2015). "Serum Dclk1 levels were also increased in the pancreatic cancer KPC mice." (PMID 25723399, 2015). "We first found that expression of the pancreatic tumor-initiating/cancer stem cells (CSC) marker DclK1 occurs in early stage PC and in both early and late pancreatic intraepithelial neoplasia (PanIN) and that it increases as disease progresses in GEM and also in human PC." (PMID 25906749, 2015). "Here we sought to determine whether DCLK1 protein can be detected in the bloodstream and if its levels in archived serum samples could be quantitatively assessed in pancreatic cancer patients." (PMID 25723399, 2015). "Quantification of DclK1-positive cells in pancreatic tumor from control diet-fed mice showed 80 ± 1.34 (mean ± SEM), as compared with 45 ± 1.54 and 30 ± 1.25 in tissue from mice treated with low or high dose licofelone, for a decrease in cancer stem cells by 43% and 62% (P > 0.0001), respectively." (PMID 25906749, 2015). "In this report, we sought to determine whether DCLK1 protein can be detected in the bloodstream and if its levels in archived serum samples could be quantitatively assessed in pancreatic cancer patients and in PDAC mouse model." (PMID 25723399, 2015). "We have previously reported that DCLK1 is upregulated in pancreatic tumor tissues and co-localizes with vimentin, a marker of mesenchymal lineage within premalignant PanIN lesions, suggesting that these DCLK1+ cells are of mesenchymal origin or in the process of EMT." (PMID 25723399, 2015). "Following the knockdown of DCLK1, we observed a significant downregulation of let-7-dependent luciferase activity indicating that NPsiDCLK1 regulates downstream targets of let-7 in pancreatic cancer cells." (PMID 24040120, 2013). "DCLK1 regulates EMT in human pancreatic cancer cells via a miR-200a dependent mechanism and is also a regulator of let-7a in pancreatic and colorectal cancer cells, which supports the concept that these miRNAs are relevant and novel targets in several solid tumor cancers." (PMID 24040120, 2013). "Interestingly, a recent molecular study revealed that inhibition of DCLK1 could downregulate PD-L1 expression through the Hippo-YAP1 signaling pathway in human pancreatic cancer." (PMID 39781521, 2025). "In addition, the protein products resulting after proteolytic cleavage of DCLK1 by calpain and caspases 3/7 may also lead to pro-tumorigenic processes as recently demonstrated for the short isoforms of DCLK1 in colon, gastric, lung and pancreatic cancer." (PMID 36979969, 2023). "DCLK1 isolation, identification, and targeting as an oncogenic driver indicates that DCLK1 may promote tumor heterogeneity and metastatic spread in colon and pancreas carcinomas." (PMID 35717205, 2022).
pancreatic cancer (continued). "Notably, a small molecule LRRK2 inhibitor, LRRK2-IN-1, demonstrated activity in colorectal and pancreatic cancer via direct inhibition of DCLK1; the clinical utility of such therapeutic agents could also spawn further from LRRK2-overexpressed cases." (PMID 32722212, 2020). "Previous studies reported that DCLK1 level in colorectal, gastric, pancreatic, breast, and esophageal cancers and clear renal cell carcinoma is higher in tumor tissues compared with adjacent tissues, and it can predict poor survival in kidney and pancreatic cancers." (PMID 31979136, 2020). "In addition, DCLK1 expression was observed to be occur in early stage pancreatic cancer and in both early and late pancreatic intraepithelial neoplasia (PanIN) and that it increases as disease progresses in genetically engineered mouse models and also in human pancreatic cancer." (PMID 26673007, 2016). "Interestingly, DCLK1 is considered as a putative pancreatic stem cell marker and is up-regulated in pancreatic cancer, colorectal cancer and many other solid tumors, and might be a candidate for developing chemotherapeutic agents." (PMID 26161641, 2015). "DCLK1 has been identified as a specific marker of CSC in various gastrointestinal cancers including colon cancer, pancreatic cancer, and esophageal cancer." (PMID 38980538, 2024). "In the presence of oncogenic KRAS, IL-17 induces transcription of DCLK1 and ALDH1A1 (a marker of embryonic stem cells) through classical pathway activation, and directly upregulates DCLK1 expression in pancreatic cancer cells in a dose-dependent manner." (PMID 39839479, 2024). "DCLK1 activates EMT and promotes the migration and invasion of pancreatic cancer cells, while knockdown of DCLK1 reduces the expression of EMT transcription factors in these cells." (PMID 36902253, 2023). "Accumulating evidences showed that DCLK1 was overexpressed in several types of tumours, especially in CRC9, 10, 11, 12, 13, 14, 15 and pancreatic cancer." (PMID 35522902, 2022). "Another study showed that glycolysis promotes the expression of DCLK1 and maintains the CSC and EMT phenotypes via low reactive oxygen species levels in chemo-resistant pancreatic cancer cells." (PMID 33348546, 2020). "To further evaluate DCLK1 protein expression in PDAC tumors, we performed immunohistochemistry using anti-DCLK1 antibody on a commercially available tissue microarray with tumor and normal adjacent tissues (NAT) from stages I/II pancreatic cancer patients." (PMID 31467540, 2019). "Recently, DCLK1 has been identified as a cancer stem cell (CSC) marker and was overexpressed in many types of cancer, including colorectal cancer, pancreatic cancer, esophageal cancer, renal clear cell carcinoma (RCC), and breast cancer." (PMID 31223610, 2019). "In summary, the studies reported here illustrate the role of DCLK1 in KRAS activation, PDAC tumor cell invasion, drug resistance, pancreatic tumor growth in vivo, and overall patient survival." (PMID 31467540, 2019). "According to these findings, it was concluded that DCLK1, as a potential KRAS effector, functionally contributes to the pathogenesis of pancreatic cancer." (PMID 29156578, 2017). "It has been reported that DCLK1 (a putative marker for pancreatic and intestinal cancer stem cells) regulates EMT in human pancreatic cancer cells through a mechanism dependent on miR-200a." (PMID 27006664, 2016). "Doublecortin-like kinase 1 (DCLK1) is a tumor stem cell marker in colon cancer, pancreatic cancer, and likely other cancers that is overexpressed in hypoxic conditions." (PMID 25605241, 2015). "We have demonstrated that DclK-1 (DCAMKL-1), is a novel putative pancreatic stem cell marker and identified DclK-1 as potent target for pancreatic tumor eradication." (PMID 25906749, 2015). "Doublecortin-like kinase 1 (DCLK1) is a putative pancreatic stem cell marker and is upregulated in pancreatic cancer, colorectal cancer, and many other solid tumors." (PMID 25723399, 2015).
pancreatic cancer (continued). "To assess the functional effects of LRRK2-IN-1 in vitro we chose to focus on the AsPC-1 human pancreatic cancer and HCT116 human colon cancer cell lines, which are both well characterized for their DCLK1 expression in the literature." (PMID 24885928, 2014). "Doublecortin-like kinase 1 (DCLK1) is emerging as a tumor specific stem cell marker in colorectal and pancreatic cancer." (PMID 24885928, 2014). "As previous studies have shown that targeting DCLK1 with kinase inhibitors resulted in significant reduction of clonogenic potential and invasive capacity in pancreatic cancer and renal cell carcinoma cell lines, we next assessed the impact of LRRK2-IN-1 induced DCLK1 inhibition on HNSCC cell lines." (PMID 34336664, 2021). "DCLK1, which has been suggested as a marker for ductular cells during pancreatic cancer development, did not stain the epithelial branching structures, but instead decorated clusters of cells outside of them." (PMID 30814526, 2019). "With these data, we speculate that DCLK1 plays a role in post-transcriptional regulation of miR-143/145 cluster and thereby downregulates KRAS and RREB1 in pancreatic tumor xenografts." (PMID 24040120, 2013). "Nakanishi and his colleagues pointed out that DCLK1 was specially expressed on intestinal CSCs rather than normal stem cells, which made DCLK1 a promising target for CSCs suppression, and the initiating role of DCLK1 in tumorigenesis was subsequently identified in pancreatic cancer (PC)." (PMID 37069669, 2023). "In addition, DCLK1, another marker of CTC, may also be used in the early diagnosis of pancreatic cancer." (PMID 37007078, 2023). "Notably, these correlations were independent of tumor histological subsites, and are in line with previous reports suggesting that DCLK1 is involved in regulating of the NOTCH, KRAS, WNT, and TGFβ pathways to promote progression, EMT, and self-renewal in colorectal and pancreatic cancer cells." (PMID 34336664, 2021). "It is possible that either a lower DCLK1-S expression, or an altered DCLK1-L expression, in the late stage of pancreatic cancer could explain the lack of DCLK1-IN-1 activity in the remainder of these samples." (PMID 34545159, 2021). "Knockdown of DCLK1 with siRNA or downregulation of DCLK1 with a kinase inhibitor (XMD8-92) results in decreased expression of angiogenic markers/VEGF receptors (VEGFR1 and VEGFR2) and EMT-related transcription factors ZEB1, ZEB2, Snail and Slug in pancreatic tumor xenografts." (PMID 33348546, 2020). "Expression of mutant RAS in DCLK1+ cells is not sufficient to cause their transformation, but experimental induction of pancreatitis reprograms RAS mutant DCLK1+ cells in CSCs able to rapidly produce overt pancreatic cancer." (PMID 29853913, 2018). "DCLK1 specific ELISA, western blotting, and immunohistochemical analyses were used to determine expression levels in the serum and staining intensity in archived tumor tissues of pancreatic ductal adenocarcinoma (PDAC) patients and in pancreatic cancer mouse models." (PMID 25723399, 2015). "Therefore, inhibition of glycolysis signalling, up‐regulation of ROS generation and/or silencing of DCLK1 may be effective approaches to eliminating CSCs, reversing the EMT phenotype and thus eradicating chemoresistant cancer cells to improve the prognosis of patients with pancreatic cancer." (PMID 28244691, 2017).
colorectal cancer (49 papers, 2010 to 2025). A primary or metastatic malignant neoplasm that affects the colon or rectum. "The DCLK1 gene is located on human chromosome 13, and its upregulation is associated with the prognosis and metastasis of colorectal cancer." (PMID 38254219, 2024). "For example, DCLK1 is not only associated with GC but also with colorectal cancer, where it can promote the epithelial-mesenchymal transition process." (PMID 33737947, 2021). "Moreover, a KRAS synthetic lethal screening previously identified the related kinase DCLK2 as a hit in the colorectal DLD-1 cell line, suggesting DCLK1 as a potential target for combination therapy in the context of KRAS-mutated colorectal cancer." (PMID 31681616, 2019). "Moreover, in the presence of relevant mutations, DCLK1+ cells become the cell of origin for inflammation-associated pancreatic and colorectal cancers." (PMID 30899515, 2019). "In colorectal cancer, high baseline DCLK1 expression predicts radioresistance and poor treatment response, supporting its use as a companion biomarker." (PMID 40563698, 2025). "Dclk1 also marks the stemness of colorectal cancer, researchers found that when depleting Dclk1+ stem cells in colorectal cancer, liver metastases were significantly inhibited." (PMID 41346572, 2025). "DCLK1-IN-1 is a highly selective DCLK1 kinase inhibitor that has been shown in multiple experiments to inhibit the aggressiveness and stemness of colorectal cancer and reverse chemotherapy resistance." (PMID 38254219, 2024). "Overexpression of DCLK1 which was previously reported to be remarkable in cell progression and metastasis of colorectal cancer, was also found to be a significant prognostic factor on BCa." (PMID 37196048, 2023). "Doublecortin-like kinase 1 (DCLK1), a microtubule associated protein kinase, is overexpressed in colorectal cancer and specifically marks cancer stem cells (CSCs) in the intestine." (PMID 36210463, 2022). "Rationale: Doublecortin-like kinase 1 (DCLK1) is a serine/threonine kinase that selectively marks cancer stem-like cells (CSCs) and promotes malignant progression in colorectal cancer (CRC)." (PMID 35910805, 2022). "The oncogenic role of doublecortin-like kinase 1 (DCLK1) as a putative cancer stem cell (CSC) marker has been clarified in colorectal cancer (CRC)." (PMID 35717205, 2022). "Another study has demonstrated that the expression of FXYD3 was reduced in colorectal cancer cells with overexpression of DCLK1, thus representing a novel therapeutic target for colorectal cancer." (PMID 33350586, 2021). "Doublecortin-like kinase 1 (DCLK1) is a serine/threonine kinase that is upregulated in a wide range of cancers, including colorectal cancer and gastric cancer." (PMID 34924565, 2021). "Hypoxia is a key regulator of the TME and evidence indicates that DCLK1-positive colorectal cancer cells have increased stemness in hypoxic conditions." (PMID 33348546, 2020). "DCLK1 is frequently overexpressed in colorectal cancer and has been identified as a colorectal cancer stem cell specific marker, whose depletion promotes polyps regression." (PMID 31681616, 2019). "Doublecortin-like kinase 1 (DCLK1) labels tumor stem cells (TSCs) in genetic mouse models of colorectal cancer (CRC)." (PMID 31878090, 2019). "A recent study showed that DCLK1 mediates the pro-survival signaling and self-renewal of colorectal cancers." (PMID 29652830, 2018). "Recent studies provided evidence that DCLK1 promotes the epithelial–mesenchymal transition via the PI3K/AKT/NF-kB pathway in colorectal cancer cells." (PMID 29652830, 2018). "Recent reports have displayed that DCLK1 is a marker of differentiated cells and an epigenetic biomarker of intestinal cancer stem cell in colorectal cancer." (PMID 29297280, 2017). "Upregulation of DCLK1 expression in blood circulation was found in chemoradiotherapy-treated colorectal cancer patients." (PMID 26621833, 2016).